NF1 (neurofibromin 1)
Diseases named in the same sentence as NF1 in open-access papers (continued):
Sharing a sentence is not in itself a finding about the gene and the disease.
RASopathies (continued). "NF1 belongs to RASopathies, a clinically defined group of genetic syndromes caused by germline mutations in genes that encode components or regulators of the Ras/mitogen-activated protein kinase (RAS–MAPK) pathway." (PMID 31487937, 2019). "Altered glial number and function are observed in response to RASopathy-linked Nf1, Ptpn11/Shp2, and Ras mutations." (PMID 31017896, 2019). "The patient with the high mutational burden had a RASopathy profile, showing a NF1 mutation, together with truncation of RASA2, leading to increased activation of Ras." (PMID 31500314, 2019). "NF1 is the first and most studied RASopathy in animal models, and several of the key NF1-associated phenotypes have been recapitulated using model organisms." (PMID 26203125, 2015). "NF1 belongs to a group of disorders referred to as the RASopathies, caused by germline mutations in components of the RAS/MAPK pathway that all give rise to an increased cancer risk." (PMID 24386979, 2014). "We find enrichment in RASopathy mutations for NF1, while RASA1 and SHOC2 have mainly cancer mutations." (PMID 24803665, 2014). "Other RASopathies have been associated with pulmonary stenosis, including NF1." (PMID 40437629, 2025). "Here we describe the 34 mutation-positive cases with RASopathy (excluding NF1), to put forward the molecular spectrum of RASopathies, as well as some other syndromes (n = 5) which may clinically mimic RASopathies owing to their overlapping features." (PMID 41292581, 2025). "The high irritability levels found in children with Rasopathies in our study, along with the similar levels between NS and NF1, could imply an undiscovered association between irritability and the RAS-MAPK pathway dysregulation." (PMID 39764141, 2024). "While irritability scores were similar between the Rasopathies groups, we demonstrated different influences of NS and NF1 status on the associations between irritability and ADHD symptoms and social skills impairments, potentially suggesting differences in the mechanisms underlying these processes." (PMID 39764141, 2024). "Inactivation or functional loss of NF1 may also cooperate with other so-called RASopathy genes—such as SPRED1, which is involved in melanoma genesis —in sustaining constitutive RAS activation." (PMID 36900152, 2023). "Therefore, NF1 is considered a member of the RASopathies, a group of genetic conditions caused by mutations in genes encoding for members of the RAS/mitogen-activated protein kinase (MAPK) pathway." (PMID 36923276, 2023). "Previous work has elucidated specific behaviors impacted by RAF1 and NF1 RASopathy mutations." (PMID 34222248, 2021). "In addition, Nf1 loss or HRAS-G12V RASopathy mutations have also been shown to impact mature and myelinating oligodendrocytes." (PMID 34222248, 2021). "Hence, many clinical laboratories now offer large RASopathy panels that include the NF1 and SPRED1, and this study quantifies the diagnostic yield of such testing." (PMID 32107864, 2020). "Interestingly, one patient showed a RASopathy profile with NF1 truncation and mutations in RASopathy genes like RASA1 and RASA2, which is known from cutaneous melanoma." (PMID 31500314, 2019). "The consistently high prevalence of ADHD across both NF1 and NS raises important questions about its role in the neurobehavioral phenotype of RASopathies." (PMID 40725498, 2025). "Background/Objectives: Neurofibromatosis type 1 (NF1) and Noonan syndrome spectrum disorders (NSSD) are the most common RASopathies, resulting from germline mutations that affect the RAS-MAPK signaling pathway." (PMID 40725498, 2025). "Molecular confirmation of the NF1 was essential to avoid misdiagnosing NF-NS as other RASopathies with overlapping features, such as café-au-lait spots and lentigines, seen in Legius syndrome, NS, NS with multiple lentigines, and heterozygous LZTR1 variants." (PMID 40289159, 2025).
RASopathies (continued). "As an initial step, we calculated the correlations between irritability and social skills impairments first in the Rasopathies and TD groups and subsequently in the NS, NF1, and TD groups." (PMID 39764141, 2024). "The models were first applied to the entire dataset, with Rasopathies as the group variable, and subsequently applied to NS and TD, NF1 and TD, and NS and NF1 groups." (PMID 39764141, 2024). "An important amount of research results has already been published describing the ASD phenotype of NF1, while this cannot be said about the other RASopathies." (PMID 38581124, 2024). "Irritability is associated with emotional dysregulation-related disorders in Rasopathies with variable influences of NS and NF1 status." (PMID 39764141, 2024). "Continued reporting will help clarify the relationship between IBD and RASopathies such as NF1 and LS." (PMID 37927732, 2023). "This explains why NF1 is included in the group of RASopathies and shares several clinical features with Noonan syndrome." (PMID 36831560, 2023). "In NF1, as in other RASopathies, although yet debated, increasing paternal age has been associated with a higher risk for de novo mutations." (PMID 35723633, 2022). "Mutations in Ras-MAPK pathway genes including NF1, Ras, MEK, and RSK, together referred to as Rasopathies, cause syndromic autism." (PMID 34021030, 2021). "This is consistent with studies of other mouse models for RASopathies, where normal social approach behaviors have been seen in Raf1L613V mice, KRasG12V mice and Nf1+/− mice." (PMID 34311771, 2021). "RASopathies, including NF1, NS, Costello syndrome, and cardiofaciocutaneous syndrome, are a group of distinct diseases that are caused by mutations that upregulate the RAS/MAPK pathway." (PMID 34222248, 2021). "The RASopathy Neurofibromatosis type 1 (NF1) is a major syndromic form of ASD, resulting from mutations in the NF1 gene encoding for neurofibromin, a negative regulator of Ras." (PMID 34311771, 2021). "RASopathies also include NF1 (OMIM code #162200) and LS (OMIM code #611431), caused, respectively, by inactivating mutations of NF1, which encode for a GTPase activating protein, and SPRED1, which is a negative mediator of RAS-mediated RAF 1 activation." (PMID 33718303, 2021). "Of the known RASopathies, we focus on Noonan syndrome (NS) and neurofibromatosis type 1 (NF-1), conditions about which most data has been collated in the literature." (PMID 28694877, 2017). "In order to utilize a separate approach to assess evidence for multiple genetic hits contributing to ASD symptoms, we ascertained individuals for having a RASopathy (NF1, NS, CS, and CFC)." (PMID 28076348, 2017). "Searching for co‐occurring mutated genes revealed the RASopathy genes PTPN11 and RASA2, as well as another RAS domain‐containing gene RASSF2 enriched in the NF1 subtype after adjustment for mutational burden." (PMID 28267273, 2017). "Herein, we confirmed that mutations in the RASopathy genes RASA2 and PTPN11 were enriched in the NF1 subtype and also identified RASSF2, a RAS domain‐containing gene, as enriched in the NF1 subtype." (PMID 28267273, 2017). "Some of these genes increase predisposition to cancer, for example, in rasopathies, and BRAF, KRAS, HRAS, NF1, NRAS PTPN11, RAF129." (PMID 27080396, 2016). "In summary, our observations and those described in previously published reports support the indication of molecular testing of NF1 and other RASopathies genes in cases in which the diagnosis of RASopathy is uncertain or in which the phenotype is borderline." (PMID 24767283, 2014).
RASopathies (continued). "In contrast, MMS typically predominantly manifests as a secondary vasculopathy within monogenic disease frameworks, where primary genetic defects (e.g., JAG1 in Alagille syndrome, NF1 in RASopathies) disrupt cerebrovascular homeostasis through pathway-specific mechanisms." (PMID 40508049, 2025). "Of the 10 missense PVs, 80% were previously reported as being associated with NF-NS, specifically NF1 p.(Arg1809) (50%, 2 families), p.(Arg1276) (20%, 2 families) and p.(Lys1423) (10%) No PVs were found in other RASopathies-related genes." (PMID 40289159, 2025). "Importantly, they recapitulated phenotypes identified in Rasopathy models with upstream Ras activation, such as neurofibromatosis type 1 (NF1): oligodendrocyte lineage defects, reactive astrogliosis, memory deficits, and hypersensitivity to sensory stimuli." (PMID 41446112, 2025). "Genomic ascertainment of electronic health record-linked exome data in two large biobanks was used to quantify germline pathogenic/likely pathogenic (P/LP) variant prevalence, cancer prevalence, and survival in adults with non-NF1 RAS/mitogen-activated protein kinase genes (RASopathies)." (PMID 39802765, 2024). "Patient 8 and 11 also had full RASopathy panel screening and were found to not have any other variant except the variant identified in the NF1 gene." (PMID 38596211, 2024). "Future mechanistic research, including other Rasopathies besides NS and NF1, is needed to support our hypothesis." (PMID 39764141, 2024). "NS and NF1 are common RASopathies with a combined frequency of ∼1 in 2000 births." (PMID 38826084, 2024). "Estimations of Sanger sequencing prices were performed for five genes most commonly associated with RASopathies (BRAF, NF1, PTPN11, RAF1, and SOS1), and three genes, TCOF1, CHD7, and NIBPL most commonly associated with Treacher Collins, CHARGE, and Cornelia de Lange syndromes, respectively." (PMID 37815686, 2024). "Importantly, the presence of CAs allows for the differentiation of NF1 from Legius syndrome, the RASopathy with the greatest overlap with NF1." (PMID 37686284, 2023). "RASopathies may arise de novo; however, germline transmission may also occur, especially in NF1 and NS, two of the most common RASopathies." (PMID 35103797, 2022). "LS, therefore, is a RASopathy with clinical features similar to NF1." (PMID 35178568, 2022). "Further bolstering this hypothesis, a recent clinical study compared the ASD phenotype across three RASopathies, NF1, Noonan syndrome and cardiofaciocutaneous syndrome (CFC), which each stem from mutations in different regulators of the RAS-MAPK pathway." (PMID 34311771, 2021). "Sequencing of all 14 RASopathy‐associated genes in the 505 patients in the validation cohort identified 11 (2%) patients with disease‐causing variants and 15 (3%) patients with a VUS (n = 11) or VUS‐likely benign (n = 4) in the NF1 or SPRED1 genes." (PMID 32107864, 2020). "All the phenotypes in our patient can be explained by the RASopathies, e.g., NF1 and NS, and age and environmental factors may play roles in onset of NFNS phenotype, which makes it difficult to diagnose without genetic testing." (PMID 32357851, 2020). "In subjects with a clinical suspicion of a RASopathy or neurocutaneous disorder, the mutation detection rate was 72.2% (26/36), with variants distributed in ten different genes, mainly PTPN11 (22.2%), and with only one causative variant in NF1 (2.7%)." (PMID 31370276, 2019). "Similarly, a relatively small percentage of children in the RASopathy groups (15% for NS and 5% for NF1) scored in the severely impaired range (SS ≤ 70) on the SSIS." (PMID 29914349, 2018). "NS and NF1 are the two most common and extensively studied RASopathies." (PMID 29914349, 2018). "NF1 thus belongs to the group of Ras pathway syndromes, the Rasopathies." (PMID 29335026, 2018).
RASopathies (continued). "Furthermore, it also enabled us to determine if there were differences in phenotype- or treatment efficacy compared to other mouse models of RASopathies caused by mutations in up-stream regulators of HRAS protein, such as NF1, SHP2/PTPN11, and SPRED1." (PMID 28455524, 2017). "Besides NF-1, other RASopathies include Noonan syndrome, Costello syndrome, and Legius syndrome." (PMID 40563584, 2025). "Finally, using NF1 as a platform to uncover cell- and tissue-specific RAS-dependent signaling pathways is likely to improve our understanding of the molecular pathology associated with other RASopathies or other RAS-driven cancers." (PMID 35188187, 2022). "An alternative, ‘MEKi-in-milk’ protocol, in which the drug is given to lactating mothers, has been employed effectively in mouse models of NF1, and may represent a strategy to deliver MEK inhibitors at an earlier developmental stage in non-NF1 RASopathy models." (PMID 35178568, 2022). "Therefore, despite the modest increase in molecular diagnosis in our study (increased from 23.5% to 25.7% in the validation cohort with an overall positive rate = 3.2% (17/533) for both cohorts), patients with a suspected RASopathy should be tested on an NGS panel that includes the NF1 and SPRED1." (PMID 32107864, 2020). "Furthermore, there is a clinical overlap between certain RASopathies and NF1, and multigene testing may be warranted in such cases." (PMID 31507634, 2019). "For example, RASopathies, such asNoonan syndrome, Neurofibromatosis 1 and Leopard syndrome, are a subtype ofdevelopmental diseases characterized by mutations in genes encoding for components ofthe Ras/MAPK pathway (NF1, PTPN1, SOS1, RAF1,KRAS, NRAS, SHOC2, CBL)." (PMID 29719609, 2018). "In contrast, children in both RASopathy groups were rated as having significantly poorer social skills relative to unaffected siblings [NS vs. siblings: mean difference = − 13.2; 95% CI − 20.1, − 6.3; p < 0.001] [NF1 vs. siblings: mean difference = − 11.8; 95% CI − 18.4, − 5.2; p < 0.001]." (PMID 29914349, 2018). "In addition, it will be important to assess whether mGluR-LTD is altered the NF1, Legius Syndrome, or Noonan syndrome RASopathy mouse models." (PMID 28455524, 2017). "In addition to NF1, individuals with Noonan syndrome and other RASopathies could be more vulnerable to developing myeloid diseases after exposure to benzene." (PMID 24386979, 2014). "More than 90% of JMML cases harbor germline or somatic mutations in one of five canonical driver genes-PTPN11, NRAS, KRAS, NF1, or CBL-establishing JMML as the prototypical malignant manifestation of RASopathy biology." (PMID 42193013, 2026). "The commonality of cancer and RASopathies prompted MEK (MAPK kinase) inhibitors and Ras-targeted therapies for some RASopathies like selumetinib for NF1 patients." (PMID 37925498, 2023). "Osteoclast dysregulation in RASopathies is indirectly suggested by studies of Neurofibromatosis Type 1 (NF1), where haploinsufficiency of RAS negative regulator NF1 gene leads to an increased RAS activation." (PMID 36330334, 2022). "Within RASopathies, an intellectual disability diagnosis was much more frequent in CFCS and CS than in NS and NF1, consistent with previous literature." (PMID 35021989, 2022). "Mutations are found in the Ras signal transduction pathway downstream of the receptor in about 90% of patients; thus, JMML belongs to the group of diseases called RASopathies (Noonan syndrome, CBL-syndrome, NF1)." (PMID 33672937, 2021). "BRAF, CBL, NF1, PTPN11, RAF1, SOS1 and SOS2 contain at least 20 phosphosites each, and they account for 326 of the phosphosites identified in RASopathy proteins (61% of the total)." (PMID 34229750, 2021).
RASopathies (continued). "In this context, ERAS adds up to the list of genes whose mutation can lead to overgrowth syndromes (as AKT, PIK3CA, PTEN) or RASopathies (as H-RAS, RASA1, NF1 and RAF1, among others)." (PMID 34771750, 2021). "This 24% is higher than the one observed for other RASopathy proteins, including but not limited to PPP1CB, and similar to NF1." (PMID 34229750, 2021). "Cost‐benefit considerations support adding the NF1 and SPRED1 to the Noonan spectrum disorder/RASopathy NGS gene panels." (PMID 32107864, 2020). "Adding the NF1 and SPRED1 genes to Noonan spectrum disorder/RASopathy NGS gene panels modestly increases clinical diagnoses without significantly increasing the VUS burden." (PMID 32107864, 2020). "The addition of the NF1 and SPRED1 genes to Noonan spectrum and RASopathy gene panels should reduce the time to diagnosis for such individuals and allow for appropriate medical management." (PMID 32107864, 2020). "Because of their functional significance RAS signaling pathway components including NRAS, KRAS, NF-1, PTPN11, and CBL were summarized as RASopathy genes within one category." (PMID 32344757, 2020). "Since a diagnosis of NF1 or LS would change patient management, the NF1 and SPRED1 genes should be included on all to Noonan spectrum disorder/RASopathy NGS gene panels, including those used prenatally." (PMID 32107864, 2020). "Since a diagnosis of NF1 or LS would change patient management, NF1 and SPRED1 should be included on all Noonan spectrum disorder/RASopathy NGS gene panels." (PMID 32107864, 2020). "For children with a suspicion of NF1 who do not yet meet the clinical diagnostic criteria at an early age, molecular testing of NF1 is not only helpful to confirm the diagnosis but also beneficial for differential diagnosis between Rasopathies and other diseases sharing overlapping features." (PMID 31717729, 2019). "Rasopathy patients, including those with Costello, Noonan, LEOPARD, and cardiofaciocutaneous (CFC) syndromes and NF1, can have heart and/or bone abnormalities." (PMID 24035394, 2013). "Given the elevated risk of CHM, especially pulmonic stenosis, proactive cardiovascular assessment similar to other RASopathies is recommended for NS-NF patients, regardless of NF1 PV type." (PMID 40289159, 2025). "The astrocyte-specific deletion of Nf1, however, did not impair spatial memory in mice, suggesting that only specific RASopathy genes are critical for astrocytic function." (PMID 39964758, 2025). "Three patients in the ESTAND cohort had findings in pleiotropic genes SPRED1, NF1, and LZTR1 linked to developmental syndromes referred to as RASopathies, including various cancerous and non-cancerous tumors as part of the respective syndromic phenotype." (PMID 40060932, 2025). "This pathway has not been extensively studied in the context of RASopathies, but in NF1, ROCK plays a crucial role in regulating actin cytoskeleton dynamics and cell contractility." (PMID 39201250, 2024). "NF1 was the first disorder identified to implicate a gene involved in the RAS/mitogen-activated protein kinase (RAS-MAPK) pathway, and is thus considered a RASopathy." (PMID 38596211, 2024). "Because of the lack of typical NF1 features (i.e., Lisch nodules and neurofibromas) and elements that suggested a particular RASopathy, a molecular analysis of SPRED1 was launched when he was 11 years of age." (PMID 24767283, 2014). "The lifespan of individuals with RASopathies is unknown as this question has not been systematically evaluated; however, it is known that those with NF1 do have a shorter life span due to cancer morbidity." (PMID 35103797, 2022). "We clinically and genetically investigated 281 patients, almost all pediatric cases, presenting with either NF1 (n = 150), only pigmentary features (café au lait macules with or without freckling; (n = 95), or clinical suspicion of other RASopathies or neurocutaneous disorders (n = 36)." (PMID 31370276, 2019).